RPL22 (ribosomal protein L22)
Diseases named in the same sentence as RPL22 in open-access papers (continued):
Sharing a sentence is not in itself a finding about the gene and the disease.
tumor (31 papers, 2016 to 2025). "Here, we report our finding that the loss of Rpl22, which serves as a tumor suppressor in some hematologic malignancies, results in the induction of its paralog RPL22L1." (PMID 31581233, 2019). "Secondly, RPL22 has been identified as a potential tumor suppressor gene that is mutated or deleted in T‐ALL and several epithelial tumor types." (PMID 28264936, 2017). "This commentary discusses the emerging dual roles of RPs in ribosome biogenesis and tumor suppression, with a focus on RPL22’s role in the splicing of MDM4." (PMID 40427096, 2025). "Recent functional studies suggest RPL22 acts as a haploinsufficient tumor suppressor involved in inducing senescence through CDK4 inhibition." (PMID 35012638, 2022). "Probably, the accumulation of Drp1-enriched RPL22 in the cytoplasm resulted in the disorder of mitochondrial dynamics, inducing over-proliferation of tumor cells." (PMID 35230214, 2022). "At the molecular level, these tumor characteristic mutations included PTEN (88%), RPL22 (33%), KRAS (35%), PIK3CA (54%), PIK3R1 (40%), and ARID1A (37%) with high TMB levels (18 × 106 Muts/Mb) and certain TIL." (PMID 36578004, 2022). "In the TCGA database, RPL22 was shown to be expressed at lower levels in tumor relative to control breast tissue samples, with such downregulation being correlated with poorer prognosis." (PMID 34178640, 2021). "Five tumor suppressor genes have variants (RNF43 G659fs, NPM1 W288fs, RPL22 K15fs, ACVR2A K437fs, LARP4B T163fs) that occur in over 5% of samples in at least one cohort." (PMID 34214079, 2021). "When we assessed RPL22 levels via Immunofluorescence of TNBC patient tumor and control tissues and via qPCR in 62 TNBC tissue samples, we confirmed that this RP was present at lower levels in tumor tissues." (PMID 34178640, 2021). "We have previously reported that RPL22 functions as a tumor suppressor in T-acute lymphoblastic leukemia." (PMID 31581233, 2019). "Recently we also discovered that RPL22 functions as a haploinsufficient tumor suppressor in T-cell acute lymphoma/leukemia (T-ALL)." (PMID 31581233, 2019). "For example, alterations in RPs such as RPL5 (uL5), RPL10 (uL16), RPS15 (uS19), RPL11 (uL15), and RPL22 (eL22) have been described in 10–40% of multiple tumor types." (PMID 31590378, 2019). "Cluster 9 also included all microsatellite instable (MSI) ENOC tumours, and was also associated with MMRD-1, Age, and Del signatures, along with higher numbers of SNVs, and KMT2B and RPL22 mutations." (PMID 30794536, 2019). "In this study, RPL22 was mutated in 11% of tumours, all of which were MSI being a frequent event in MSI tumours (5/9, 56%)." (PMID 30894686, 2019). "Interestingly, the overlapping Drp1- and RPL22-positive area was notably reduced (red rectangular frame), and the intracellular distribution of RPL22 has an endonuclear location in the Mdivi-1-challenged tumor tissues (green rectangular frame)." (PMID 35230214, 2022). "Possibly, the increased nuclear RPL22 may bind to the downstream tumor suppressor genes in the nucleus, exerting an effective anti-tumor role." (PMID 35230214, 2022). "Moreover, alterations of RPL5, RPL10, RPS15, RPL11, and RPL22 ribosomal proteins have been described in 10 to 40% of tumor types." (PMID 33462193, 2021). "We next conducted rescue experiments to confirm whether RPL22 was involved in ADAMTS9-AS2-mediated suppression of TNBC tumor growth." (PMID 34178640, 2021). "Intriguingly, EBER-1 that also interacts and re-localizes RpL22 only partially restored MDV-induced tumor formation, suggesting that this interaction could indeed play a minor role in the cellular transformation." (PMID 29317752, 2018).
tumor (continued). "The interaction between vTR and RpL22 could play an important role in tumor formation and should be addressed in future studies." (PMID 28677643, 2017). "Co-occurring CN loss and hypomethylation events were more prevalent in LUSC, affecting TSGs including NCOR1 (29 of 59 tumor regions), CDKN2C (28 of 59 tumor regions), CREBBP (26 of 59 tumor regions) and RPL22 (9 of 59 tumor regions)." (PMID 40931149, 2025). "Identification of novel tumor-wide neoantigens from RNA splicing erros, such as GNAS and RPL22, enhances T cell therapy by recognizing and eradicating cancer cells across various tumor types." (PMID 40563429, 2025). "The other ribosomal protein gene transcripts identified in mouse mammary gland to correlate with ZFAS1, i.e. RPS21, RPS24, RPL22 and RPL28, showed significant expression differences between normal and tumour samples (*P < 0.05, **P < 0.01, ***P < 0.001, ****P < 0.0001)." (PMID 27871336, 2016). "Furthermore, our investigations into the direct effects of ribosomal biogenesis on metastasis, through depletion of the ribosomal protein component Rpl22 or rRNA transcription factor Ubf, did not result in alterations in tumor phenotypes." (PMID 38722825, 2024). "Because no commercial antibodies against RPL22 or RPL22L1 gave reliable IHC results in patient tumor samples, we developed an anti-human RPL22L1 polyclonal antibody and verified its specificity and its function in immunoblotting, immunofluorescent staining, and immunohistochemistry." (PMID 31581233, 2019).
infection (6 papers, 2012 to 2025). The state of being infected such as from the introduction of a foreign agent such as serum, vaccine, antigenic substance or organism. "In contrast, RPL22/eL22-transduced cells showed a peak of TR reduction at day 7 post infection, and a progressive recovery 12- and 14-days post-infection." (PMID 34676390, 2021). "Additionally, late in infection, eL22/RPL22 and ICP4 co-localize in discrete, clustered structures within the nucleus of the infected cell." (PMID 39766272, 2024). "It should be noted that ISGs with antiviral activity in control cells might not appear as antiviral in ZAP cells due to infection rates being near the 85% cutoff (e.g. CCL2), or due to a failure to meet our analysis criteria in ZAP cells (e.g. RPL22)." (PMID 22615998, 2012).
immune disorders (1 paper, 2021). "Although previous studies reported that RPL22 might act as a protective factor to promote cell senescence under physiological conditions, while in pathological conditions such as inflammation were caused by immune disorders." (PMID 34220863, 2021).
RPL22 also shares sentences with these, for which no sentence is quoted: melanoma (4 papers); glioma (3); gastric tumors (2); hepatocellular carcinoma (2); multiple myeloma (2); myelodysplastic syndrome (2); ovarian carcinoma (2); adenocarcinoma (1); adenoma (1); Allergy (1); Alzheimer disease (1); biliary tract cancer (1); cardia cancer (1); chronic lymphocytic leukemia (1); colorectal tumors (1); Diamond-Blackfan anemia (1); experimental autoimmune encephalomyelitis (1); gastric adenocarcinoma (1); gastric adenoma (1); gastritis (1); hematologic malignancies (1); liver cancer (1); lupus nephritis (1); macrocytic anemia (1); major depression (1); meningioma (1); mesothelioma (1); mismatch repair deficiency (1); myeloid leukemia (1); non-small cell lung carcinoma (1).
A further 5 diseases each share a sentence with RPL22 in 1 paper.